ATF4 (activating transcription factor 4)
Diseases named in the same sentence as ATF4 in open-access papers (continued):
Sharing a sentence is not in itself a finding about the gene and the disease.
pancreatic cancer (continued). "Additionally, we aimed to explore the role of ATF4 under glutamine metabolic stress and reasoned that ATF4 upregulates ASCT2, a glutamine transporter, thereby enhancing the survival of pancreatic cancer cells." (PMID 40223274, 2025). "Similarly, inhibition of the MAPK pathway reduces ATF4 translation and ASNS expression, increasing the sensitivity of pancreatic tumors to asparagine restriction." (PMID 38495490, 2024). "Further studies using siRNA‐mediated gene silencing showed that ATF4 and TXNIP were essential for GW3965‐induced REDD1 expression, while REDD1 was critical for GW3965‐mediated antiproliferation and pro‐death activities in pancreatic cancer cells." (PMID 38089448, 2022). "Furthermore, we performed an analysis of the mRNA expressions on REDD1, ATF4, and TXNIP from pancreatic cancer samples and the matching normal pancreatic tissues (the Oncomine database)." (PMID 38089448, 2022). "Most importantly, we uncovered the significance of ATF4/TXNIP/REDD1/mTOR signaling in the control of the biological activities of GW3965, which was corroborated by expressional analysis on xenograft tumor samples as well as human tissues of pancreatic cancer." (PMID 38089448, 2022). "In our study, we found that ATF4 is overexpressed in PDAC tissues and pancreatic cancer cell lines." (PMID 33782384, 2021). "Fisetin in murine xenograft pancreatic cancer PANC‐1 cells inhibits PANC‐1 cell proliferation, enhances AMPK/mTOR signaling pathway and stress‐induced transcription factor p8, induces autophagy, and increases the ATF4 and ATF6." (PMID 33473265, 2021). "Gene enrichment analysis showed that by blocking eIF2a phosphorylation and reducing ATF4 translation, acriflavine inhibited the unfolded protein-responsive PERK/eIF2a/ATF4 pathway, that is, acriflavine restored the drug sensitivity of acquired drug-resistant pancreatic cancer cell lines." (PMID 37790807, 2023). "In pancreatic cancer cells, however, not only was AMPK level or its activation (p‐AMPK) altered by GW3965 treatment but knocking down AMPK by siRNA did not affect REDD1 level in response to GW3965, suggesting the specificity of ATF4 and TXNIP in regulating REDD1 and mTOR in these cancer cells." (PMID 38089448, 2022). "The well‐demonstrated role of mTOR signaling in diverse human cancers and its regulation controlled by ATF4‐induced TNXIP‐stabilized REDD1 prompted us to examine the potential involvement of ATF4/TXNIP/REDD1/mTOR signaling in GW3965‐induced biological activities in pancreatic cancer cells." (PMID 38089448, 2022). "In this study, we demonstrated that CB-839 effectively inhibited cell growth in pancreatic cancer cells, but activated the general control nonderepressible 2 (GCN2)-activating transcription factor 4 (ATF4) signaling pathway." (PMID 40223274, 2025). "To assess the clinical relevance of our observations, we first compared the mRNA expressions of ATF4, TXNIP, and REDD1 on the basal level between immortalized but nontumorigenic HPNE cells and pancreatic cancer cells." (PMID 38089448, 2022).
Sepsis (30 papers, 2017 to 2025). Sepsis is defined as life-threatening organ dysfunction caused by a dysregulated host response to infection. "A report illustrated that SESN2 shields dendritic cells from sepsis-induced ferroptosis through the ATF4-CHOP-CHAC1 signaling pathway." (PMID 39037665, 2025). "In macrophages, ATF4 has been identified as a key glycolytic activator that contributes to the inflammatory response in sepsis by binding to the promoter region of Hk2." (PMID 39870616, 2025). "To further clarify the role of ATF4 in the in vivo sepsis model, we utilized ATF4 shRNA for macrophage reconstitution in the LPS-induced sepsis mouse model." (PMID 40384854, 2025). "For instance, research has shown that activating transcription factor 4 (ATF4) plays a significant role in regulating glucose metabolism in macrophages during sepsis." (PMID 40005571, 2025). "Our study identifies SREBF1 as a master regulator of DC dysfunction in sepsis by inducing lipid biosynthesis-driven ER stress via the PERK/eIF2α/ATF4/CHOP axis." (PMID 40524162, 2025). "Our study demonstrated that HSF represents a promising strategy for treating sepsis-induced intestinal injury, since it can promote ATF4-mediated self-regeneration of the intestine by increasing the crypt/enterocyte proliferation and migration." (PMID 40822467, 2025). "In the early stages of sepsis, activating transcription factor 4 (ATF4) regulates macrophage pro-inflammatory response activation through direct targeting of HK2 or interaction with HIF-1α to maintain its stability." (PMID 39234245, 2024). "Inducing ATF4 expression can induce immune activation in tolerant macrophages, providing new insights for immune reconstitution therapy in sepsis." (PMID 39234245, 2024). "In this study, we found that in sepsis, ER stress activates ATF4, which in turn upregulates CIRP expression." (PMID 39465383, 2024). "Studies have indicated that SESN2 can suppress ferroptosis of DCs in sepsis by downregulating the Atf4/Chop/Chac1 signaling pathway (Li J.-Y." (PMID 39944356, 2024). "Based on the presented findings, we propose that ER stress, induced by sepsis or LPS stimulation in macrophages, triggers ATF4 activation, which subsequently enhances the expression of CIRP." (PMID 39465383, 2024). "Further research demonstrated that SESN2 protected DCs against sepsis-induced ferroptosis through an activating transcription factor 4 (ATF4)–C/EBP homologous protein (CHOP)–cation transport regulator homolog 1 (CHAC1)-dependent manner." (PMID 38816685, 2024). "SESN2 can play an antioxidant role in sepsis, downregulating the ATF4-CHOP-CHAC1 signaling pathway and inhibiting ferroptosis in dendritic cells." (PMID 36685932, 2022). "Second, the potential effects of SESN2 and ATF4 double knockdown in sepsis models need to be further tested." (PMID 34741186, 2021). "Our previous report verified that SESN2 alleviates excessive inflammation and dysfunction of DCs by interacting with ATF4 to decrease the extent of ERS during sepsis." (PMID 34741186, 2021). "Emerging evidence suggests that lncRNA OIP5-AS1 modulates ATF4 signaling in sepsis-induced ALI." (PMID 40777108, 2025). "Additionally, SESN2 suppresses DC ferroptosis in sepsis by downregulating the ATF4-CHOP-CHAC1 signaling pathway, suggesting antioxidative potential." (PMID 38348451, 2024). "Sestrin2 protects dendritic cells from sepsis-induced ferroptosis and may act as an antioxidant by downregulating the ATF4/CHOP/CHAC1 signaling pathway." (PMID 38023615, 2023). "Moreover, SESN2 deficiency strongly aggravated ERS responses in DCs during sepsis, as evidenced by upregulation of GRP78 and ATF4 in CLP mice." (PMID 32071292, 2020). "Here, our results show that HO-1 could inhibit ER stress and reduce intrapulmonary cell apoptosis after sepsis through suppression of the PERK/eIF2-α/ATF4/CHOP pathway." (PMID 30013453, 2018). "This ATF4 response may be an important pathway linking sepsis-mediated MODS to mitochondrial dysfunction." (PMID 28549777, 2017).
Sepsis (continued). "In addition, we also found that ATF-4 inhibition could be invoked as a potential therapeutic for sepsis-induced acute liver dysfunction." (PMID 37122356, 2023). "By reducing the expression of the PERK/ATF4/CHOP signaling pathway, the NLRP3 inflammasome’s hyperactivation and caspase-1-dependent pyroptosis are inhibited, which improving sepsis outcomes." (PMID 38434710, 2024). "In the sepsis mouse model, the activation of the PERK/ATF4/CHOP signaling pathway trigger NLRP3/caspase-1-mediated pyroptosis and the generation of pro-inflammatory cytokines, leading to elevated mortality rates among septic mice." (PMID 38434710, 2024). "Herein, we found that the apoptosis of T lymphocytes in sepsis was closely related to UPR-related proteins, including GRP78, ATF4 and CHOP." (PMID 36873287, 2023). "Therefore, ATF4 might be a regulator involved in inflammation response during sepsis." (PMID 33177520, 2020). "The anti-inflammatory effect of glycolysis inhibitor 2-DG on AMs during sepsis was mediated by GDF15 via inducing the phosphorylation of the α-subunit of eukaryotic initiation factor 2 (eIF2α) and the expression of activating transcription factor 4 (ATF4)." (PMID 38725041, 2024). "Similarly, in interaction with the activating transcription factor 4 (ATF4), HIF-1 improves the immune activity of macrophages involved in sepsis." (PMID 38001795, 2023). "Our findings indicated that the expression of ERS components (GRP78, ATF4, and CHOP) was significantly upregulated in DCs after the initiation of sepsis, showing the same tend as inflammasome activation, hinting at a relationship between PERK–ATF4–CHOP signaling and CASP-1-mediated pyroptosis." (PMID 34741186, 2021). "Thus, we speculated that HO-1 protects sepsis-induced ALI and alleviates intrapulmonary cell apoptosis through suppression of the PERK/eIF2α/ATF4/CHOP proapoptosis pathway in ER stress." (PMID 30013453, 2018). "Dusp, SphK1, IL10, ATF4, VEGF, CEBP, PGC1a, and PPARg were not significantly affected by sepsis (data not shown)." (PMID 32477273, 2020).
viral infection (30 papers, 2013 to 2025). "Our findings provide new insights into the mechanism of autophagy caused by viral infection via ER stress and reveal an antiviral drug target, ATF4, that contributes to the BVD eradication program." (PMID 36939351, 2023). "Nrf2 is activated mainly by electrophiles or reactive oxygen species (ROS), whereas ATF4 is activated by divergent stresses, including heme deficiency, viral infection, ER stress, and amino acid deficiency." (PMID 30959808, 2019). "We propose that the viral infection-induced host response of amino acid deficiency induces ATF4 expression." (PMID 28465428, 2017). "The precise role of ATF4 during viral infection is unclear and depends on cell hosts, viral agents, and models." (PMID 38534416, 2024). "In this context, it has been shown that numerous viral infections modulate ATF4 activity, which contributes to or represses viral replication, depending on the virus and the targeted host cell." (PMID 38534416, 2024). "The PERK-eIF2α-ATF4 pathway is a crucial branch of ER stress that gets activated following viral infection." (PMID 39233905, 2024). "In this review, we summarize the ATF4-mediated signaling pathways in response to viral infections, focusing on human immunodeficiency virus 1 (HIV-1)." (PMID 38534416, 2024). "Fourth, viral infection leads to abnormal kinase expression, and autophagy or apoptosis is regulated by the eIF2α-ATF4 pathway to promote viral proliferation." (PMID 32703221, 2020). "Here, we discuss that viral infection induces autophagy or apoptosis through the eIF2α-ATF4 pathway." (PMID 32703221, 2020). "Increased levels of ATF4 during early stages of viral infection can have a direct impact on establishing early viral reservoirs due to its ability to induce viral transcription." (PMID 28465428, 2017). "To further examine the changes in ATF4 expression in response to early viral infection, we expanded our analysis to in vitro primary human CD4+ T cells following HIV infection and measured the induction of ATF4 expression." (PMID 28465428, 2017). "Moreover, PKR not only contributes to the early stage of eIF2α phosphorylation but also elicits eIF2α-ATF4-CHOP signaling in ERS-induced apoptosis during viral infection." (PMID 40145089, 2025). "Also, nitazoxanide can induce ATF4 upregulation, which results in Nrf2 expression, a factor that protects cells against oxidative damage and thus against viral infection." (PMID 38785529, 2024). "By highlighting the involvement of ATF4 in viral infections, this study gives valuable insights that could be used for further strategies to tackle viral infections, providing a deeper understanding of host–pathogen interactions." (PMID 38534416, 2024). "Furthermore, ATF4 can also participate in the establishment of innate and adaptive immunity that is essential for the host to control viral infections." (PMID 38534416, 2024). "Despite its key role at the crossroads of immune and stress responses, the precise impact of ATF4 during viral infections remains unclear." (PMID 38534416, 2024). "Upon sensing various stimuli such as tRNA deficiency, viral infection, ER stress, and oxidative stress, ISR kinases phosphorylate eIF2α, which up-regulates activating transcription factor 4 (ATF4) and promotes cellular reprogramming toward survival or apoptotic pathways." (PMID 38803225, 2024). "Given the known interplay of Atf4 and Nrf2, it is possible that Nrf2 may activate similar or unidentified responses to antagonize viral infection, even in the presence of a dampened type I IFN response and will require further investigation." (PMID 35198887, 2022). "Whereas the ISR was activated during early phase of infection, PERK-eIF2α phosphorylation was differentially upregulated during late phase of infection, indicating a functional dichotomy of PERK-eIF2α phosphorylation and ATF4-CHOP in different phases of virus infection." (PMID 34106769, 2021).
viral infection (continued). "In addition to ER stress, the eIF2α/ATF4 pathway can be engaged by other stimuli involving kinases stimulated by viral infections, metabolic alterations, among other factors, suggesting a broad function of the eIF2α/ATF4 pathway as a stress integrator." (PMID 23874395, 2013). "Finally, we also consider that ATF5, the paralogue of ATF4 in mammals, could be a potent actor during viral infections." (PMID 38534416, 2024). "Furthermore, ATF4 signaling can be hijacked by pathogens to favor viral infection and replication." (PMID 38534416, 2024). "Additionally, viral-responsive mRNA transcription and translation-related genes were also significantly enriched in UESL and several of the most highly enriched transcriptional factor gene sets such as ATF4 and YB-1 can also be induced as a response to viral infection." (PMID 32310940, 2020). "Viral infection can activate PERK and PKR, which phosphorylate eIF2α and therefore induce ATF4 expression." (PMID 26565589, 2015). "ATF4 expression is not only induced by PERK activation but also by three other cytosolic eIF2α-kinases (PKR, HRI and GCN2), which are activated under viral infection or nutrient starvation conditions." (PMID 25393282, 2014). "However, ATF4, CHOP and BIP were also up-regulated, suggesting that a more general ER stress/UPR was activated by viral infection in macrophages." (PMID 32418990, 2020). "Moreover, in HCAEC endothelial cells, the EDEM1 mRNA—an ER stress-induced factor that disposes of misfolded proteins—was upregulated 24 and 48 h following infection, but not in Grp78, CHOP, and ATF4, indicating differences regarding the ER stress response mechanism during the virus infection." (PMID 38785529, 2024). "To rule out potential non-specific effects of the shRNAs or of the viral infection, we also injected animals with two control lentiviral constructs (control 1, a scrambled form of ATF4-shRNA and control 2, an ineffective ATF4 shRNA targeted to the rat ATF4 sequence but not the mouse ATF4 message)." (PMID 25071442, 2014).
neuroblastoma (29 papers, 2012 to 2026). Neuroblastoma (NB) is the most common solid, extracranial childhood tumor. "More recently it was reported that vimentin upregulates the expression of p21Waf1, a cyclin-dependent kinase inhibitor in neuroblastoma, and inhibits osteocalcin gene expression in association with activating transcription factor-4 (ATF4) in osteoblasts." (PMID 22229032, 2012). "Corrector Vx-809 treatment significantly reduced (p < 0.005) TG-induced ATF4 levels, confirming its effect on ATF4 activation in neuroblastoma cells." (PMID 39329905, 2024). "Insulin resistance induces overexpression of ER stress indicators such as p-eIF2, ATF4, CHOP, sXBP1, p-IRE1, and p-ASK1 at the mRNA or protein level, causing neuronal cell death in neuroblastoma cells." (PMID 38982468, 2024). "To determine how O-GlcNAcylation affects ATF4 and its signaling, we subjected the neuroblastoma cell line (SH-SY5Y) and cervical cancer cells (Hela) to long-term TMG treatment (10 μm) for at least 3 weeks prior to harvesting." (PMID 38192280, 2023). "MYCN can also drive transcription of ATF4 in neuroblastoma cells, and it was demostrated that targeting either MYCN or ATF4 leads to decreased expression levels of PHGDH, PSAT1, SHMT2, MTHFD2, and MTHFD1L." (PMID 37949226, 2023). "We show that TMG elevates ATF4 protein levels upon mitochondrial stress in SH-SY5Y neuroblastoma and HeLa cell-lines." (PMID 38192280, 2023). "In another layer of evaluation, we detected MYCN binding across the ATF4 locus, an anticipated result since the MYCN–ATF4 axis is one of the well-addressed TF interrelationships in neuroblastoma." (PMID 37835497, 2023). "The expression of CBS, CTH, SLC3A2, and SLC7A11 is transcriptionally upregulated by KDM4C and ATF4 in neuroblastoma cells, leading to a significant increase in the intracellular levels of cysteine." (PMID 36077650, 2022). "ATF4 also cooperates with enzymes that control histone methylation states for transcriptional activation of serine-glycine pathway genes in neuroblastoma cells." (PMID 36077650, 2022). "Analysis of patient data reveals significantly higher ATF4 mRNA levels in neuroblastoma tumors with MYCN amplification and higher ATF4 expression is associated with poor prognosis in neuroblastoma patients." (PMID 36077650, 2022). "Elevated ATF4 expression is a common feature of neuroblastoma cells with MYCN amplification and is responsible for the activation of the serine–glycine synthesis pathways essential for cell survival." (PMID 32310340, 2020). "In brief, we reveal that the down-regulation of CHERP induces apoptosis in neuroblastoma cells by activating the ATF4/CHOP/DR5 signaling axis and inhibiting the AKT/mTOR signaling pathway." (PMID 29113358, 2017). "Similarly, N-Myc has been shown to drive an increased expression of ASCT2 in MYCN-amplified neuroblastoma cells, along with activating transcription factor 4 (ATF4)." (PMID 38399253, 2024). "Moreover, OGT knockdown (KD) in SH-SY5Y neuroblastoma cells elevates ATF4 and ATF5 mRNA and protein expression." (PMID 38192280, 2023). "Interestingly, the ISR effector ATF4 was already shown to mediate cell death upon glutamine deprivation in MYCN-amplified neuroblastoma." (PMID 37973789, 2023). "While these reports have shown that loss of BOK affects a specific branch of UPR signaling, such as IRE1- or PERK-eIF2α-ATF4-signaling, our data indicate that BOK deficiency influences indeed all three UPR-signaling branches in the neuroblastoma-derived cell lines." (PMID 36060797, 2022). "In neuroblastoma cells, ATF4 cooperates with the histone lysine demethylase KDM4C to transcriptionally upregulate the expression of enzymes for synthesis of eight non-essential amino acids, including alanine, arginine, asparagine, aspartate, cysteine, glutamate, glycine, and serine." (PMID 36077650, 2022).